STIM1 (stromal interaction molecule 1)
Diseases named in the same sentence as STIM1 in open-access papers (continued):
Sharing a sentence is not in itself a finding about the gene and the disease.
dilated cardiomyopathy (6 papers, 2018 to 2022). Cardiomyopathy which is characterized by dilation and contractile dysfunction of the left and right ventricles. "We have shown that mice with a cardiomyocyte deletion of STIM1 (crSTIM1−/−) develop ER stress, mitochondrial, and metabolic abnormalities, and dilated cardiomyopathy." (PMID 35179826, 2022). "Cardiomyocyte-STIM1-specific knockout mice exhibit dilated cardiomyopathy and cardiac fibrosis with increased stress biomarkers and altered organelle morphology in the heart, suggesting that STIM1 can regulate myocardial development and heart function." (PMID 34445487, 2021). "However, an independent analysis of STIM1 deficiency-associated dilated cardiomyopathy in mice demonstrated significantly upregulated expression of ER stress response factors, possibly reflecting mild but chronic Ca2+ store depletion that may be difficult to measure in acutely isolated cells." (PMID 32086252, 2020). "Other report showed that STIM1-KO hearts exhibits ER dilatation, disorganization of mitochondrial size and as consequence the development of a dilated cardiomyopathy, revealing an essential role of STIM1 for normal cardiomyocyte function." (PMID 29618985, 2018).
liver cancer (6 papers, 2017 to 2025). An epithelial or non-epithelial malignant neoplasm that arises from the liver. "Briefly, this study provides phylogenetic evidence for a possible HBV-driven epigenetic remodeling that alters the expression pattern of Ca2+ homeostasis-associated genes in STIM1- or Orai1 overexpressing liver cancer stem-like cells for a possible mutual survival outcome." (PMID 36556285, 2022). "We were surprised to find that some studies have shown that in the hypoxic environment of liver cancer cells, hypoxia-induced HIF-1a promotes STIM1 expression and SOCE in liver cancer cells by directly binding to the STIM1 promoter." (PMID 36187789, 2022). "STIM1 has many roles in tumorigenesis, as its silencing suppressed tumor migration or metastasis in breast, cervical, prostate, colorectal, brain, skin and liver cancers." (PMID 30544747, 2018).
nasopharyngeal carcinoma (6 papers, 2013 to 2024). A carcinoma arising from the nasopharyngeal epithelium. "Orai1/STIM1 complex is implicated in breast, nasopharyngeal carcinoma, cervical and glioblastoma multiforme tumor cell migration in vitro and in a mouse model of metastases generated by tumor xenografts." (PMID 24204345, 2013). "Increasing a long non-coding RNA can inhibit autophagy in cancer cells, and upregulating the PTBP1/STIM1 axis promotes the stemness of nasopharyngeal carcinoma cells." (PMID 39759147, 2024). "For example, down-regulation of STIM1/Orai1 counteracts the apoptosis of nasopharyngeal carcinoma cells induced by NaBu." (PMID 29089467, 2017).
COVID-19 (5 papers, 2022 to 2024). A disease caused by infection with severe acute respiratory syndrome coronavirus 2. "Of importance, this study provides a comprehensive analysis of circulatory immune factors governing the COVID-19 pathology, and identifies key roles of sCD40, sTIM-1, and Galectin-9 in predicting mortality." (PMID 39376569, 2024). "While sCD40 is central in all defined profiles, the variations in distribution of four sICPs (sCD30, s4-1BB, sTIM-1, sB7-H3) and their interactions with additional paraclinical and clinical variables help distinguishing between the different subgroups of COVID-19 patients." (PMID 39376569, 2024). "We conducted in vitro experiments in healthy donor PBMCs to verify our findings on altered KCNA3, ORAI1, and STIM1 gene expression in dexamethasone-treated COVID-19 patients and confirmed that in vitro treatment with dexamethasone altered the abundance of these ion channel encoding genes." (PMID 37033961, 2023). "In addition, to the perturbation of mitochondrial calcium sequestration, we noted that several transcripts involved in calcium transport, such as STIM1 and L-type calcium channels, were upregulated in COVID-19 PBMCs." (PMID 35005527, 2022). "Interestingly, whereas sPD-L1 and sTIM-1 levels had decreased after the patients had recovered, the level of sMMP-7, a molecule that is a better biomarker, was still high 8 months post-COVID-19." (PMID 35327637, 2022). "STIM1 expression was not altered in mild or severe COVID-19 patients compared to healthy controls, but severe COVID-19 patients with dexamethasone displayed increased gene expression." (PMID 37033961, 2023). "Additionally, sTIM-1 (soluble T-cell immunoglobulin and mucin protein-1), the soluble form of the co-stimulatory T cell receptor TIM-1 (TIM-1) known to be a key regulator of Th2 responses, showed at least 3-fold increase in moderate and severe COVID-19 cases." (PMID 39376569, 2024).
lung adenocarcinoma (5 papers, 2020 to 2022). A carcinoma that arises from the lung and is characterized by the presence of malignant glandular epithelial cells. "Moreover, STIM1 and Orai3 play a prominent role in lung adenocarcinoma, where they modulate proliferation and apoptosis, respectively." (PMID 33333945, 2020). "Likewise, the in vitro, treatment with CDDP enhanced Orai3, but not Orai1 nor STIM1 or STIM2 expression in two lung adenocarcinoma cell lines: A549 and H23 cells." (PMID 34065942, 2021).
multiple myeloma (5 papers, 2017 to 2023). "In multiple myeloma patients, overexpression of STIM1/Orai1 was closely linked with shorter progression-free survival." (PMID 37259313, 2023). "Overexpression of STIM1/Orai1 in multiple myeloma patients was closely associated with the shorter progression-free survival." (PMID 31252656, 2019). "Similarly, STIM1/ORAI1 overexpression in multiple myeloma or upregulation of ORAI1 in esophageal squamous cell carcinoma is associated with poorer progression-free survival." (PMID 34572262, 2021). "Similarly, in multiple myeloma cells, inhibition of SOCE or silencing of STIM1 or Orai1 reduced cell viability and caused cell cycle arrest and apoptosis." (PMID 31252656, 2019). "For instance, STIM1 or Orai1 is overexpressed in tumor tissues when compared with noncancerous or precancerous tissues in patients with breast, cervical, colorectal, liver, lung, clear cell renal cancers, or multiple myeloma." (PMID 31252656, 2019). "Growing evidence has shown that numerous cancer types, including liver, lung, ovarian, breast, colon, and gastric cancer, as well as multiple myeloma, manifest increased SOCE and augmented expression of STIM1 or Orai1." (PMID 37259313, 2023).
ovary carcinoma (5 papers, 2014 to 2023). "A study using paired ovarian carcinoma cell lines with different cisplatin sensitivities showed that SOCE participates in therapy resistance through elevated Orai1/STIM1 expressions and SOCE activity, accompanied by increased AKT activity." (PMID 31252656, 2019). "The present study disclosed the expression of Orai1 and STIM1 in both, therapy sensitive A2780 and therapy resistant A2780cis ovary carcinoma cells." (PMID 25015419, 2014). "In conclusion, Orai1/STIM1 expression and function are increased in therapy resistant ovary carcinoma cells, a property at least in part due to enhanced Akt activity and contributing to therapy resistance in those cells." (PMID 25015419, 2014). "More importantly, the present observations revealed that expression of both, Orai1 and STIM1, was significantly higher in therapy resistant A2780cis than in therapy sensitive A2780 ovary carcinoma cells." (PMID 25015419, 2014). "Orai1/STIM1 have been shown to be upregulated in ovarian cancer cells resistant to chemotherapy." (PMID 32785177, 2020). "The present study explored whether Orai1 and STIM1 are expressed in ovary carcinoma cells and whether their expression and function differs between therapy resistant and therapy sensitive ovary carcinoma cells." (PMID 25015419, 2014). "RT-PCR was employed to explore whether ovary carcinoma cells transcribe Orai1 and/or STIM1 and whether the transcript levels are different between therapy sensitive A2780 and therapy resistant A2780cis ovary carcinoma cells." (PMID 25015419, 2014). "We explored whether therapy resistant (A2780cis) differ from therapy sensitive (A2780) ovary carcinoma cells in Akt, Orai1, and STIM1 expression, Ca2+-signaling and cell survival following cisplatin (100μM) treatment." (PMID 25015419, 2014). "Previous studies have identified that Orai1/STIM1 expression and SOCE are increased in ovary carcinoma cells, while Akt dependent upregulation of SOCE contributes to the therapy resistance." (PMID 32079527, 2020). "Additional experiments attempted to elucidate mechanisms accounting for the differences in Orai1 and STIM1 abundance as well as SOCE between therapy resistant A2780cis and therapy sensitive A2780 ovary carcinoma cells." (PMID 25015419, 2014). "Furthermore, the expression of Orai1/STIM1, as well as SOCE activity, is enhanced in cisplatin-resistant ovarian carcinoma cells when compared with the therapy-sensitive parental cells." (PMID 31252656, 2019).
pancreatic adenocarcinoma (5 papers, 2019 to 2023). "ORAI1 and STIM1 are anti-apoptotic in pancreatic adenocarcinoma cell lines and siRNA-mediated depletion of ORAI1 and STIM1 increased apoptosis induced by 5-fluorouracil (5-FU) or gemcitabine." (PMID 30917547, 2019). "A similar observation was made in STIM1-KD pancreatic adenocarcinoma cells." (PMID 34155535, 2021). "In pancreatic adenocarcinoma, both Stim1 and Orai1 mediate SOCE and have a pro-survival anti-apoptotic role, as Orai1 and/or Stim1 silencing by siRNA enhance 5-Fluoro-Uracile (5-FU) and gemcitabine induced apoptosis." (PMID 30884858, 2019).
Stroke (5 papers, 2014 to 2025). Sudden impairment of blood flow to a part of the brain due to occlusion or rupture of an artery to the brain. "Previous studies of SHR-A3 have indicated a stroke susceptibility locus in the region of Chr1 containing the Stim1 mutation." (PMID 32300198, 2020). "Assessment of histological measures of renal injury in salt-loaded SHR-A3(Stim1 B2) congenic line in comparion with SHR-A3 under the same conditions indicates that Stim1 participates in the pathogenesis of renal injury in addition to its contribution to stroke susceptibility." (PMID 32300198, 2020). "The “beneficial” role of STIM1 is also underscored by the evidence that in stroke-prone spontaneously hypertensive rat (SHRSP), the reduction in glial STIM1 is associated with the exaggerated sympathetic response leading to stroke." (PMID 34685498, 2021). "In the present study, we show the involvement of genetic variation affecting the store-operated calcium signaling gene, Stim1, in the pathogenesis of stroke in SHR." (PMID 32300198, 2020). "For instance, dysfunction in STIM1/TRPML1 interaction participates in ALS and stroke pathogenesis through organellar ionic dysfunction." (PMID 34685498, 2021). "Stim1 is a key lymphocyte activation signaling molecule and contains functional variation in SHR-A3 that diverges from stroke-resistant SHR-B2." (PMID 32300198, 2020). "Collectively, considering the relevance of Ca2+ dyshomeostasis in neurodegeneration, the validation of new drugs toward STIM1 targets may result in successful treatment strategies for AD, PD, HD, ALS and stroke." (PMID 34685498, 2021). "The contribution of defective Stim1 function to renal injury may accelerate the elevation of blood pressure during salt loading in SHR-A3 as a result of amplified renal injury and the effect of elevated blood pressure may be a primary mechanisms of stroke pathogenesis." (PMID 32300198, 2020).
viral infection (5 papers, 2021 to 2024). "We hypothesized that during viral infection HRV 2B reduces the ER Ca2+ stores causing STIM1 to translocate into junctional areas and thus releasing STING." (PMID 35301296, 2022). "Our results showed that viral infection led to overexpression of many host proteins, among which we found STIM1 to be of particular interest as STIM1 modulates ER Ca2+ levels directly." (PMID 35891504, 2022). "To date, several studies have suggested that many viral infections result in STIM1-mediated changes in Ca2+ levels." (PMID 35891504, 2022). "Interestingly, the development of TFH cells in mice with T cell-specific deletion of Stim1/2 was severely impaired after acute viral infection or immunization." (PMID 38578569, 2024). "Interestingly, STIM1 acts a calcium sensor in the ER, and NS6 is primarily located at the ER/ERGIC in the context of virus infection, allowing for its interaction with STIM1 and the regulation of Ca2+ homeostasis." (PMID 34199223, 2021). "Viral infection of NPC cells led to higher levels of phosphorylated ERK1/2 after EGF treatment, which STIM1 knockdown partially reversed." (PMID 34684224, 2021). "Our previous study demonstrated that PDCoV regulates the calcium influx to facilitate viral infection and that an interaction of PDCoV NS6 with STIM1 necessary for the modulation of SOCE occurs." (PMID 34199223, 2021).
anemia (4 papers, 2015 to 2024). A reduction in the number of red blood cells, the amount of hemoglobin, and/or the volume of packed red blood cells. "Serum from Stim1/2Foxp3 (but not WT) mice caused a significant reduction of RBCs and hemoglobin levels in recipient mice demonstrating that anti-RBC autoantibodies in Stim1/2Foxp3 mice cause anemia." (PMID 30862784, 2019). "In the model of AIHA 15,36, however, STIM1 deficiency provides reduction from anemia induced by pathogenic anti-MRBC 34-3C autoantibodies of IgG2a and IgG2b subclasses." (PMID 26417434, 2015). "In this regard, bleeding disorders and/or anemia observed clinically are recapitulated in multiple STIM1 mouse models of TAM." (PMID 39420094, 2024).
anhidrosis (4 papers, 2020 to 2025). Lack of sweating or the ability to sweat when provoked by the appropriate stimulus. "Sweating depends on SOCE as patients with reduced SOCE due to mutations in either STIM1 or Orai1 suffer from anhidrosis." (PMID 39499286, 2025). "This is highlighted by the defects observed in patients with mutations in either STIM1 or Orai1—which phenocopy each other—including severe combined immunodeficiency, muscle hypotonia, ectodermal dysplasia, and anhidrosis with dry skin and heat intolerance." (PMID 39499286, 2025). "Mice lacking ORAI1 manifest reduced enamel mineralization and thinner skin with elongated keratinocytes and smaller vibrissae follicles, and the ectodermal-specific knockout of Orai1 or Stim1/Stim2 impairs SOCE and results in anhidrosis and a reduced sweat gland lumen." (PMID 33250786, 2020).
Anxiety (4 papers, 2015 to 2024). Intense feelings of nervousness, tension, or panic often arise in response to interpersonal stresses. "Mice overexpressing STIM1 displayed decreased anxiety and modifications in contextual learning while the conditional deletion of STIM1 in the forebrain induced only minor learning disabilities as assessed using the Morris water maze." (PMID 37029630, 2024). "In transgenic mice, overexpression of Stim1 leads to improved contextual learning and decreased depression- and anxiety-like behaviors." (PMID 38028628, 2023). "Together, these results reveal no locomotor defects in these three mutant mice and a higher tendency for exploratory behavior (reduced anxiety) in the double Stim1/Stim2 cKO mice apparent in the EPM." (PMID 26236206, 2015). "The double Stim1/Stim2 cKO mice, however, spent more time in the open arms than their control littermates, suggesting an increased willingness for exploration and reduced anxiety-like behavior." (PMID 26236206, 2015).
B cell lymphoma (4 papers, 2013 to 2022). "In accord, STIM1- and Orai1-deficient subjects displayed a significant propensity to develop human herpesvirus-8-dependent Kaposi sarcoma and Epstein–Barr virus-associated B-cell lymphoma." (PMID 35884372, 2022). "Impaired antitumour immunity and CTL function in Stim1fl/flStim2fl/flCd4Cre mice likely explain why human patients lacking SOCE due to mutations in the CRAC channel genes ORAI1 and STIM1 develop virus-associated malignancies such as EBV+ B cell lymphoma and HHV8+ Kaposi sarcoma." (PMID 23922331, 2013). "In several cases, chronic viral infections in ORAI1- and STIM1-deficient patients have caused Epstein–Barr virus (EBV)-positive B cell lymphoma and Human herpesvirus (HHV) 8-associated Kaposi sarcoma, suggesting that SOCE may be required for antitumour immunity by CD8+ T cells." (PMID 23922331, 2013). "As STIM1 and STIM2 differ in their expression profiles (at least in T cells) and the ER Ca2+ concentration to which they respond, this could potentially explain why only one of them, STIM2, showed a change in expression between CHL and other B cell lymphomas." (PMID 35685639, 2022).
colitis (4 papers, 2020 to 2025). Inflammation of the colon. "Notably, vanillic acid was shown to restore intestinal epithelial homeostasis in DSS-induced colitis by inhibiting CA9/STIM1-mediated ferroptosis, thereby preventing epithelial cell death and preserving barrier integrity." (PMID 40699788, 2025). "Conversely, CA9 demonstrated resistance to ferroptosis under hypoxic conditions, and vanillic acid facilitated the binding of CA9 to STIM1, thereby inhibiting ferroptosis and alleviating colitis, which were consistent with the effects observed upon overexpression of CA9." (PMID 40417738, 2025). "Using a murine T cell transfer model of colitis, we show that deletion of the CRAC channel genes Stim1, Stim2, or Orai1 in T cells prevents IBD and that the severity of intestinal inflammation correlates with the level of SOCE." (PMID 35919953, 2022). "The histological analysis of intestinal inflammation showed severe colitis in host mice that had received wildtype or Stim2‐deficient CD4+ T cells, whereas inflammation was partially reduced or absent following transfer of Orai1‐deficient and Stim1‐deficient CD4+ T cells, respectively." (PMID 35919953, 2022).
diabetes (4 papers, 2018 to 2025). "Clearly, the possible connection between impaired STIM1/SOCE activity and diabetes needs to be studied in more detail." (PMID 29335300, 2018). "The increase in STIM1 protein content in their study might not be attributed to hyperglycemia but to the hormones, growth factors, and/or transcription factors, the serum levels of which are elevated in diabetes." (PMID 35490782, 2022).
Duchenne muscular dystrophy (4 papers, 2011 to 2021). Duchenne muscular dystrophy (DMD) is a neuromuscular disease characterized by rapidly progressive muscle weakness and wasting due to degeneration of skeletal, smooth and cardiac muscle. "Meanwhile, Duchenne Muscular Dystrophy (DMD) mice (mdx animal model), have alterations in Ca2+-handling proteins involving STIM1 upregulation." (PMID 29618985, 2018). "In this respect, Duchenne muscular dystrophy patients did show an up-regulation of STIM2-mRNA levels, which is activated at more modest decreases in [Ca2+]ER than STIM1." (PMID 21798093, 2011). "This seems in contrast with the up-regulation of STIM1 and Orai1 and the increased SOCE reported in mouse models for Duchenne muscular dystrophy." (PMID 21798093, 2011). "While STIM1 and SOCE seem to be essential for skeletal-muscle development, excessive store-operated Ca2+ influx may underpin pathological conditions, like Duchenne muscular dystrophy." (PMID 21798093, 2011). "Consistent with the accumulated data from the mdx mouse model, human myoblasts isolated from Duchenne muscular dystrophy (DMD) patients showed a significant increase in SOCE but no increase in levels of TRPC1, Stim1 or Orai1." (PMID 30298191, 2019).
epidermoid carcinoma (4 papers, 2016 to 2019). "The expression of STIM1 in A549(adenocarcinoma) and SK-MES-1(squamous cell carcinoma) is in moderate level, so A549 and SK-MES-1 cell lines were then selected to assess knockdown of STIM1 expression and the following experiments." (PMID 31564210, 2019).